ABHD18 (abhydrolase domain containing 18)
Description:
Catalyzes the hydrolysis of an acyl chain from the tetra-acylated cardiolipin (CL) and produces the tri-acylated monolysocardiolipin (MLCL). Prefers CL with shorter and saturated fatty acyl chains as substrates. Together with Tafazzin (TAZ), it participates in the mechanism of CL remodeling, a process consisting of repetitive cycles of hydrolysis and reacylation of the fatty acids that make up CL, where the nascent acyl chains are replaced with longer, unsaturated chains.
Synonyms: C4orf29; FLJ21106
Tractability: Antibody: UniProt places it where antibodies can reach, with high confidence; UniProt predicts a signal peptide or a membrane-spanning region; its Gene Ontology location is reachable by antibodies, with medium confidence. PROTAC: ubiquitination databases record sites on it; its protein half-life has been measured.
Gene: Protein-coding gene on chromosome 4 (127,965,267 to 128,039,953, forward strand). Ensembl gene ENSG00000164074.
Subcellular location: Mitochondrion
Subcellular location (Human Protein Atlas): Nuclear membrane
Gene Ontology:
Cellular component: mitochondrion
Genetic constraint (gnomAD): Loss-of-function variants: 24 observed, 32.85 expected, observed/expected ratio (o/e) 0.73, 90% interval 0.53 to 1.03. The upper end of that interval is the gene's LOEUF score, 1.03, which puts it in group 4 of 6, group 1 being the genes least tolerant of losing a copy. Missense variants: 320 observed, 337.03 expected, observed/expected ratio (o/e) 0.95, 90% interval 0.87 to 1.04. Synonymous variants: 115 observed, 110.2 expected, observed/expected ratio (o/e) 1.04, 90% interval 0.9 to 1.22.
Homologues: Orthologues: macaque ABHD18 (98% identical), rabbit ABHD18 (94% identical), pig ABHD18 (94% identical), dog ABHD18 (92% identical), rat Abhd18 (92% identical), mouse Abhd18 (91% identical), guinea pig ABHD18 (91% identical), chimpanzee ABHD18 (89% identical), zebrafish abhd18 (70% identical), Drosophila melanogaster CG32112 (48% identical), tropical clawed frog abhd18 (37% identical), Caenorhabditis elegans C54G4.7 (29% identical).
Diseases named in the same sentence as ABHD18 in open-access papers:
ABHD18 is named in the same sentence as 2 diseases in open-access papers, as found by Europe PMC text mining. Sharing a sentence is not in itself a finding about the gene and the disease. The quoted sentences say what the papers report.
hepatocellular carcinoma (2 papers, 2018 to 2022). A malignant tumor that arises from hepatocytes. "The ABHD18 protein is a genetic marker for hepatocellular carcinoma (HCC) in Asian populations." (PMID 35893234, 2022).
Barth syndrome (1 paper, 2025). Barth syndrome (BTHS) is an inborn error of phospholipid metabolism characterized by dilated cardiomyopathy (DCM), skeletal myopathy, neutropenia, growth delay and organic aciduria. "Barth syndrome is associated with critically low levels of CL, directly caused by excessive CL degradation, which makes the inhibition of ABHD18 a plausible choice for drug development." (PMID 40378955, 2025). "This marks ABHD18 as a potential target for novel therapeutic approaches to Barth syndrome." (PMID 40378955, 2025).